ZP1 (zona pellucida glycoprotein 1)
Description:
Component of the zona pellucida, an extracellular matrix surrounding oocytes which mediates sperm binding, induction of the acrosome reaction and prevents post-fertilization polyspermy. The zona pellucida is composed of 3 to 4 glycoproteins, ZP1, ZP2, ZP3, and ZP4. ZP1 ensures the structural integrity of the zona pellucida.
Synonyms: ZPB1; HEL163; OOMD; OOMD1; OZEMA1
Tractability: Antibody: its Gene Ontology location is reachable by antibodies, with high confidence; UniProt places it where antibodies can reach, with medium confidence; UniProt predicts a signal peptide or a membrane-spanning region.
Gene: Protein-coding gene on chromosome 11 (60,867,542 to 60,875,693, forward strand). Ensembl gene ENSG00000149506.
Subcellular location: Zona pellucida (Processed zona pellucida sperm-binding protein 1); Cell membrane
Pathways (Reactome):
Reproduction: Interaction With Cumulus Cells And The Zona Pellucida
Gene Ontology:
Molecular function: protein binding; acrosin binding; structural constituent of egg coat
Biological process: binding of sperm to zona pellucida; prevention of polyspermy
Cellular component: egg coat; extracellular region; plasma membrane; extracellular matrix
Genetic constraint (gnomAD): Loss-of-function variants: 60 observed, 72.48 expected, observed/expected ratio (o/e) 0.83, 90% interval 0.67 to 1.03. The upper end of that interval is the gene's LOEUF score, 1.03, which puts it in group 4 of 6, group 1 being the genes least tolerant of losing a copy. Missense variants: 756 observed, 832.27 expected, observed/expected ratio (o/e) 0.91, 90% interval 0.86 to 0.96. Synonymous variants: 328 observed, 345.58 expected, observed/expected ratio (o/e) 0.95, 90% interval 0.87 to 1.04.
Homologues: Orthologues: chimpanzee ZP1 (99% identical), macaque ZP1 (94% identical), rat Zp1 (66% identical), mouse Zp1 (66% identical), rabbit ZP1 (65% identical), zebrafish zpax4 (12% identical). Paralogues in human: ZP4 (31% identical), ZP2 (21% identical), QRICH2 (13% identical), C16orf96 (11% identical).
Diseases named in the same sentence as ZP1 in open-access papers:
ZP1 is named in the same sentence as 20 diseases in open-access papers, as found by Europe PMC text mining. Sharing a sentence is not in itself a finding about the gene and the disease. The quoted sentences say what the papers report.
Infertility (10 papers, 2019 to 2024). "Genetic mutations in the ZP proteins (ZP1-4) can lead to ZP thinning or loss, resulting in infertility in patients." (PMID 38966008, 2024). "Forty-eight primary infertile women with ZP1 mutations were reported in the literature, aged from 23 to 38 years old, with a history of infertility between 2 and 11 years." (PMID 36476320, 2022). "Further, analyses of mutations in the gene encoding human zona proteins from infertile women suggest that ZP1, ZP2, and ZP3 have a role in fertility and assembly of ZP matrix." (PMID 33681199, 2021). "Two mutations in the gene encoding ZP1 [one missense variant c.247T > C (p.W83R) and one nonsense variant c.1413G > A (p.W471X)] have also been reported from infertile women who had oocytes with morphological defects." (PMID 33681199, 2021). "Here, using structure-function analysis, the authors suggest that filament cross-linking by ZP1 is required to form a stable ZP in human, and infertility mutations interfere with cross-linking." (PMID 31300655, 2019). "Here we report a characterisation of ZP1 proteins carrying mutations from infertile patients, which suggests that, in human, filament cross-linking by ZP1 is crucial to form a stable ZP." (PMID 31300655, 2019). "Our work increases the understanding of the pathogenesis of ZP1 and ZP3 gene mutations and recommends selecting a rational fertilization method of ART in combination with ZP target gene diagnosis for infertility patients in the clinic carrying ZP1 mutations and ZP‐free oocytes." (PMID 32573113, 2020). "Our study identified a heritable heterozygous mutation in ZP1 (c.326G>A p.Arg109His) from the patient (family 1 II‐2) and her father (family 1 I‐1), suggesting that this ZP1 mutation is associated with ZP loss and infertility in this patient." (PMID 32573113, 2020). "Notably, two other ZP1 variants have been found together with I390fs404X in infertile patients with empty follicle syndrome." (PMID 31300655, 2019). "Recent studies in human demonstrate that mutations in ZP1 gene are related to infertility, these mutations could affect the shuttling of glycoproteins to the secretory pathway, which would prevent the formation of the ZP around the ova, but also the formation and development of eggs." (PMID 33537315, 2020). "A mutation of ZP1 (I390fs404X) causing the protein to be truncated was detected in an infertile patient whose oocytes lacked a zona pellucida." (PMID 32573113, 2020). "The finding that hZP4-N1 is entirely monomeric explains why— —hZP4 does not functionally complement ZP1 in infertile patients carrying ZP1 mutations." (PMID 31300655, 2019). "Mutations in ZP1-3 genes have been recently associated with women infertility but the association between these PTC mutations in ZP4 and woman infertility remains to be explored." (PMID 31635692, 2019). "Although it was shown that oocytes from infertile women homozygous for the ZP1 I390fs404X mutation lack of a ZP39, the effect of the frameshift at the protein level was not investigated." (PMID 31300655, 2019). "If the sequencing result reveals a mutation in ZP1, the method of ICSI could be preferentially chosen instead of the traditional IVF method, which would greatly improve the probability of successful pregnancy via ART in infertility patients who have a ZP problem." (PMID 32573113, 2020).
female infertility (9 papers, 2019 to 2025). Diminished or absent ability of a female to achieve conception. "Glycoprotein ZP1 is a component of the oocyte’s zona pellucida (ZP), and mutations in human ZP1 are linked to female infertility." (PMID 31300655, 2019). "Most importantly, in addition to suggesting that different cross-link conformations may contribute to egg coat dynamics and function, this study provides valuable information to understand ZP1-associated female infertility and identifies human ZP1 as a possible contraceptive target." (PMID 31300655, 2019). "In the literature, ZP1, ZP2, and ZP3 gene alterations have been associated with female infertility, mainly on the grounds of ZP defects." (PMID 34501995, 2021). "Previous studies have reported that mutations in human ZP1, ZP2 and ZP3 influence their functions and result in a lack of ZP or in an abnormal oocytes and empty follicle syndrome, which leads to female infertility." (PMID 32573113, 2020). "Here, using mouse models with disrupted furin cleavage sites in ZP1, ZP2, and ZP3, we found that loss of the furin site in ZP2 caused female infertility associated with empty follicle syndrome (EFS), manifested by the failure to retrieve oocytes after ovarian hyperstimulation." (PMID 41394961, 2025). "Studies have reported that the variants in ZP1(MIM: 195000), ZP2 (MIM: 182888), and ZP3 (MIM: 182889) affect the formation of zona pellucida and result in female infertility, but there is no convincing evidence to prove that ZP4 (MIM: 613514) variant responsible for female infertility." (PMID 37052235, 2023). "Together, these findings suggested that disruption of furin‐mediated cleavage of ZP2 impairs ZP formation and perturbs the proper localization of ZP1 and ZP3, ultimately leading to female infertility consistent with EFS." (PMID 41394961, 2025).
empty follicle syndrome (6 papers, 2020 to 2025). "Mutations in the ZP1 gene can lead to two abnormal oocyte phenotypes: zona pellucida deficiency and empty follicle syndrome (EFS)." (PMID 38966008, 2024). "Homozygous or compound heterozygous mutations in ZP1 have been identified before in women with primary infertility due to the absence of the oocyte zona pellucida and in female infertility associated with empty follicle syndrome or degenerate oocytes." (PMID 32244758, 2020). "In summary, we unveiled a novel homozygous ZP1 variant in a woman with GEFS from a consanguineous family and provided genetic evidence linked to GEFS, thus further reinforcing the existence of empty follicle syndrome." (PMID 32329253, 2020). "Moreover, mutations in ZP1, ZP2, and ZP3 genes have been associated with empty follicle syndrome (EFS), marked by the absence of oocytes within follicles, highlighting the essential roles of ZP proteins not only in fertilization but also in folliculogenesis." (PMID 41394961, 2025).
breast carcinoma (1 paper, 2023). "ZP1 had not previously been used for subtype-specific assessments of intracellular zinc pools or zinc responses in breast cancer." (PMID 37111093, 2023).
colon cancer (1 paper, 2021). "In contrast, ZP1, ZP3, and ZP4 were not detectable at all or only in a small number of colon cancer specimens." (PMID 33917056, 2021).
epilepsy (1 paper, 2023). A brain disorder characterized by episodes of abnormally increased neuronal discharge resulting in transient episodes of sensory or motor neurological dysfunction, or psychic dysfunction. "However, chronic treatment with TC-G 1008 increased ZP-1 intensity in the CA3, CA1, and DG regions of the hippocampus of WT mice subjected to the PTZ-kindling model of epilepsy." (PMID 37185787, 2023).
nanophthalmos (1 paper, 2019). "We excluded two of these candidate variants, in ZP1 and PPP1R32, on the basis of the presence of homozygotes within the Genome Aggregation Database (gnomAD) and allele frequency (0.2%) being higher than the rate of severe nanophthalmos in the general population." (PMID 31048900, 2019).
ovarian diseases (1 paper, 2023). "Some DEGs in F1 ovaries are related to reproductive/ovarian diseases, particularly POI (as Wt1, Bmpr2, Zp1, Zp2) and PCOS (as Tcf21, Fst, Bmpr2)." (PMID 36982971, 2023).
Premature ovarian insufficiency (1 paper, 2023). Amenorrhea due to loss of ovarian function before the age of 40. "Among these genes, ZP1, WT1, and BMPR2 are premature ovarian insufficiency (POI) genes in humans." (PMID 36982971, 2023).
prostate carcinoma (1 paper, 2021). A carcinoma that arises from epithelial cells of the prostate gland. "Inter alia, Costa and colleagues have demonstrated that ZP1, ZP3, and ZP2, but not ZP2-specific transcripts, are expressed in prostate cancer-derived PC3 cells and prostate tumor tissue." (PMID 33917056, 2021).
cancer (1 paper, 2016). A tumor composed of atypical neoplastic, often pleomorphic cells that invade other tissues. "Most of these genes have not been previously reported in HCC, and BTBD17, MIR6089, ZNF205-AS1 and ZP1 have not previously been linked to cancer; only two genes (DAB2IP and ZNF185) have been reported in HCC." (PMID 27768594, 2016).
tumor (1 paper, 2025). "Studies have demonstrated that ZP1 is expressed in PCa cell lines such as PC3, while the ZP family has been shown to significantly influence tumor cell viability, proliferation, and migration rates." (PMID 40356901, 2025).
ZP1 also shares sentences with these, for which no sentence is quoted: infection (2 papers); atherosclerosis (1); gram-negative bacterial infections (1); male infertile (1); prostate tumor (1); reproductive diseases (1); viral infection (1); ZIKV infection (1).